ZBTB7A (zinc finger and BTB domain containing 7A)
Diseases named in the same sentence as ZBTB7A in open-access papers (continued):
Sharing a sentence is not in itself a finding about the gene and the disease.
tumor (continued). "Again, this is in line with the tumor suppressive function of the TSGs regulated by ZBTB7A." (PMID 32774369, 2020). "Furthermore, HP1γ-induced downregulation of the LRF/ZBTB7A favors the expression of several tumor-promoting factors, such as AXL receptor tyrosine kinase (AXL), plasmacytoma variant translocation 1 (PVT1), and ETS Like-1 protein (ELK1)." (PMID 31823818, 2019). "Based on the study of mice with Zbtb7a and Pten loss, which show a decrease in PTEN induced senescence (PIS) and an increase in SOX9 transcriptional activity, we investigated the expression of the tumours suppressor retinoblastoma (RB)." (PMID 29484136, 2018). "In contrast, it was more recently shown that ZBTB7A can also act as a tumour suppressor." (PMID 27252013, 2016). "Besides tumour metabolism, it is known that ZBTB7A also plays an important role in haematopoietic lineage fate decisions." (PMID 27252013, 2016). "However, ZBTB7A down-regulation promotes tumor growth in some circumstances, suggesting that it may function as a tumor suppressor by preventing tumor metabolism and limiting glycolysis via transcription in human malignancies." (PMID 38981872, 2024). "In addition, we confirmed whether the protein expression of ZBTB7A was normal in the ZBTB7A-expressing tumor using Western blotting and whether the tumor volume and weights were suppressed in ZBTB7A-expressing U343 cells compared to the control cells." (PMID 36596853, 2023). "After observation for 4 weeks, the GBM tumor volume was significantly increased in a mouse injected with shZBTB7A-expressing U87 cells compared to that in the control mice, and the protein expression levels of ZBTB7A and EPB41L5 in GBM tumor tissues were inversely correlated." (PMID 36596853, 2023). "Therefore, our results suggest that ZBTB7A acts as a tumor suppressor in GBM." (PMID 36596853, 2023). "Moreover, Zbtb7a overexpression also restored the tumor growth in vivo." (PMID 28881782, 2017). "Through transcription factor analysis, we can see that State7, 6, 5, 3, representing tumours, is enriched in STAT5B, TFAP2C, KLF1, ZBTB7A, etc.." (PMID 38613345, 2024). "When ZBTB7A was depleted in GBM cells, tumor migration and EMT-related gene expression were significantly increased." (PMID 36596853, 2023). "In experiments on mice, the researchers found that ZBTB7A inhibits expression of the EPB41L5 gene, which codes for a protein which promotes tumor growth and metastasis." (PMID 36596853, 2023). "RT-PCR ascertained miR-137 and ZBTB7A mRNA expressions in the AGS and MKN-45 cell models with PURPL overexpression and the xenograft tumor model." (PMID 35012438, 2022). "As assessed by tumor volume, knockdown of ZBTB7A significantly inhibited CRC growth, while ectopic ZBTB7A expression markedly promoted CRC cell tumorigenesis in vivo." (PMID 33167891, 2020). "Zinc finger and BTB domain containing 7A (ZBTB7A) is a transcriptional repressor of the POZ/BTB and Krüppel (POK) family transcription factors, acting as a proto-oncoprotein or a tumor suppressor, depending on the cellular context." (PMID 33007962, 2020). "As its potential pro-tumor function of ZBTB7A in CRC, the effect of ZBTB7A in cell proliferation was further investigated in vitro." (PMID 33167891, 2020). "Based on these data collected in vitro, we measured the expression level of MMP11, Zbtb7a, SIRT7 and c-Raf in tumor biopsies, focusing on those patients showing a downregulation of miR-125a of at least 2-fold." (PMID 28445974, 2017). "Considering the potential role of ZBTB7A as tumour suppressor in AML and its anti-proliferative properties, we correlated ZBTB7A expression with clinical outcome in a larger cohort of AML patients (GSE37642)." (PMID 27252013, 2016). "The tumor-suppressive mechanism of ZBTB7A is not clear and the relationship of ZBTB7A to HOTAIR has never been explored." (PMID 38981872, 2024).
tumor (continued). "However, the growth of GBM tumors was promoted by ZBTB7A knockdown, and GBM tumor volume was significantly increased in the in vivo mouse GBM model." (PMID 36596853, 2023). "ZBTB7A overexpression did not promote tumor growth in vivo in GBM models, but it suppressed the expression of EPB41L5, a target of ZBTB7A." (PMID 36596853, 2023). "ZBTB7A (Zinc Finger and BR-C, ttk and bab (BTB) Domain Containing 7A) was shown to have a crucial tumor suppressor role in the prostate by physically interacting with SOX9 and functionally antagonizing its transcriptional activity on genes involved in invasion of tumor cells." (PMID 31027362, 2019). "Additionally, in breast cancer cells, LRF/ZBTB7A has been proposed to participate in transforming growth factor beta (TGF-β) signaling, a critical pathway for tumor progression, by binding to specificity protein 1 (SP1) and downregulating Smad4 expression." (PMID 31823818, 2019). "However, it is not clear how ZBTB7A functions as a transcriptional activator or repressor of tumor growth in GBM cells." (PMID 36596853, 2023). "In addition, circPOK of zbtb7a functions as a proto‐oncogenic RNA by co‐activating the ILF2/3 complex, which operates separately and antithetically with the linear mRNA which serves as a tumor suppressor." (PMID 32608539, 2020). "However, studies also found that ZBTB7A may also interact with and repress SOX9 (sex determining region Y-box 9), various glycolytic transcription factors and a number of other targets; these findings reveal this protein's functional complexity when mediating tumor suppression." (PMID 32083004, 2020).
infection (5 papers, 2015 to 2025). The state of being infected such as from the introduction of a foreign agent such as serum, vaccine, antigenic substance or organism. "Our findings showed that the downregulation of genes controlled by the transcription factors NFYA/NFYB, ZBTB7A, and PBX3 was a common feature of cells susceptible to infection both before and after exposure." (PMID 40725231, 2025). "ZBTB7A expression is also increased in CHIKV-infected individuals during the acute phase of infection." (PMID 39311214, 2024). "Persistent viral shedding and cell survival have also been described in human coronavirus 299E infections where the transcription factor ZBTB7A controls oxidative stress to enable this infection outcome." (PMID 37971257, 2023). "ZBTB7A was selected as a representative protein with a low H/L ratio in the purified fraction, potentially indicating an increase in abundance of sumoylated forms following infection." (PMID 26200910, 2015). "Moreover, as predicted from the screen data, ZBTB7A and KMT2D were important for infection with HIV-1 envelope but had a minimal effect on infection with the HIV-1 pseudotyped with VSV-G." (PMID 36744886, 2023). "In infection-susceptible cells, genes regulated by the transcription factors NFYA/NFYB, ZBTB7A, and PBX3 were downregulated both in the presence and absence of infection." (PMID 40725231, 2025).
adenocarcinoma (1 paper, 2023). A common cancer characterized by the presence of malignant glandular cells. "The majority of the NEPC tumors co-expressed RET and ZBTB7A protein, while the adenocarcinoma tumors primarily expressed only ZBTB7A." (PMID 37065756, 2023).
neurodevelopmental disorder (1 paper, 2026). A behavioral and cognitive disorder with onset during the developmental period that involves impaired or aberrant development of intellectual, motor, or social functions. "A total of six de novo missense variants were located in genes previously identified as causal for a neurodevelopmental disorder, of which three variants in PRPF8, TRIO and ZBTB7A were classified as likely pathogenic." (PMID 40836029, 2026). "Exome sequencing analysis yielded a pathogenic variant in SPTBN1 as well as likely pathogenic variants in PRPF8, TRIO, and ZBTB7A - four genes previously implicated in neurodevelopmental disorders with or without speech problems." (PMID 40836029, 2026). "Replication in a person who stutters is required to confirm that stuttering is a feature of the monogenic neurodevelopmental disorders associated with mutations in SPTBN1, PRPF8, TRIO, and ZBTB7A, and to causally link FLT3 and IREB2 to neurodevelopmental disorders." (PMID 40836029, 2026). "According to prior literature on the genes implicated by our de novo analyses, none of the patients with neurodevelopmental disorders caused by mutations in SPTBN1, PRPF8, TRIO, and ZBTB7A have been described to stutter." (PMID 40836029, 2026).
ZBTB7A also shares sentences with these, for which no sentence is quoted: glioblastoma (2 papers); liver cancer (2); Obesity (2); Oral Carcinoma (2); B Cell CLL (1); bladder urothelial carcinoma (1); breast invasive carcinoma (1); chondrosarcoma (1); colon adenocarcinoma (1); Down syndrome (1); dysplasia (1); esophageal squamous cell carcinoma (1); fibrosis (1); head and neck squamous cell carcinoma (1); hematological cancers (1); hematological malignancies (1); ischemic cardiomyopathy (1); liver (1); liver disease (1); major depressive disorder (1); metabolic disorder (1); pancreatic cancer (1); pancreatic ductal adenocarcinoma (1); photosensitive epilepsy (1); psychiatric disease (1); rectum adenocarcinoma (1); renal carcinoma (1); sarcoma (1); schizophrenia (1); Sickle Cell Anemia (1).
A further 5 diseases each share a sentence with ZBTB7A in 1 paper.